INS (insulin)
Diseases named in the same sentence as INS in open-access papers (continued):
Sharing a sentence is not in itself a finding about the gene and the disease.
Hyperinsulinemia (continued). "In contrast to high-dose exposure models, male rats chronically exposed to low-dose monocrotophos in vivo displayed normal basal insulin secretion, increased GSIS, and increased insulin content in isolated islets, which is consistent with the pronounced hyperinsulinemia observed in vivo." (PMID 35156417, 2022). "When human insulin preparations are administered, unlike the situation of endogenous hyperinsulinism, C-peptide levels are suppressed because exogenous insulin does not contain C-peptide (as well as proinsulin)." (PMID 36376919, 2022). "Congenital forms of hyperinsulinism (CHI) can be divided into the following two main groups: channelopathies defects in ion channels located on β-cells membrane and metabolopathies defects in the metabolic pathways leading to increased insulin release." (PMID 36294341, 2022). "This profile may also occur in exogenous insulin administration, although very high C-peptide immunoreactivity will usually discriminate IAS from exogenous hyperinsulinemia." (PMID 34051096, 2021). "Around week 4, fasting hyperinsulinemia first occurred in the absence of detectable fasting glucose elevation and impaired systemic insulin sensitivity." (PMID 33817571, 2021). "In the context of our findings and the pilot studies in humans demonstrating that TRE is an effective and simple dietary intervention to improve insulin sensitivity, we suggest TRE as potential strategy for reducing hyperinsulinemia and thus tumor growth in cancer patients." (PMID 33495474, 2021). "However, some practitioners recommend more informative tests, such as euglycemic hyperinsulinemia clamp (EHC) or insulin sensitivity test (IST) that is considered the gold-standard method to assess the carbohydrates metabolism and overall insulin sensitivity." (PMID 34684619, 2021). "The hyperinsulinemia induces age-related senoinflammation via insulin-dependent Akt activation leading to organ dysfunction in non-metabolic organs, namely, the kidneys and lungs." (PMID 34631216, 2021). "Importantly, inhibition of insulin secretion with diazoxide mimics TRF whereas artificial elevation of insulin through insulin pumps implantation reverses the effect of TRF, suggesting that TRF acts through modulating hyperinsulinemia." (PMID 33495474, 2021). "Some group of researchers documented that MSG-induced dyslipidemia alters LDL/HDL ratio with the obese condition, increased adiposity without hyperphagic response, hyperinsulinemia by increased insulin level, fibrosis, and steatosis in rodants model." (PMID 34026558, 2021). "Later, and despite persistent hyperinsulinemia, glucose homeostasis is no longer regulated and cardiac insulin resistance occurs, participating in cardiac contractile dysfunctions." (PMID 33682327, 2021). "In contrast, our group showed that hyperinsulinemia did not, however, increase β-alanine uptake into human skeletal muscle when β-alanine and insulin concentrations were controlled." (PMID 34676442, 2021). "Our results showed that the abnormal increase of serum insulin level of T2D mice was significantly decreased after MBBP‐bread treatment for 7 weeks, indicating that MBBP‐bread could effectively relieve hyperinsulinemia." (PMID 34026064, 2021). "Hyperinsulinemia may downregulate insulin uptake across the BBB and reduce levels of insulin in the brain because of saturation at supraphysiological levels." (PMID 34349617, 2021). "Equal serum insulin levels were measured at 4 months of age, which were, however, significantly increased at 12 months of age for hAPP23+/− mice compared to C57BL/6 mice, indicative of hyperinsulinemia in this murine model." (PMID 34206322, 2021). "Given the role of IDE in degrading insulin, the development of IDE activators for use in subjects with hyperinsulinemia may be a potential viable pharmacological approach." (PMID 34360563, 2021).
Hyperinsulinemia (continued). "In contrast, the rates of glucose oxidation were not increased more than by hyperinsulinemia alone since, at these levels of insulin, the glucose oxidation pathway comes to saturation and glucose storage represents the major route of glucose disposal." (PMID 33419065, 2021). "Moreover, the reported increase of fasting glucose and insulin in PCOS obese patients compared to obese controls can help to suggest that abdominal fat has a critical role in developing hyperinsulinemia in PCOS patients." (PMID 34122339, 2021). "During hyperinsulinemia, 11β-dehydrogenase activity in skeletal muscle was not downregulated in response to insulin in obese men, unlike lean men." (PMID 33270115, 2021). "A previous study using both techniques evaluating the pharmacokinetics of insulin preparations has indicated that artificially established non-physiological hyperinsulinemia interferes with the PK/PD parameters of insulin preparations." (PMID 34925042, 2021). "Several factors, such as hyperinsulinemia and hyperglycemia, together with increased free fatty acid (FFA) concentrations and proinflammatory cytokine levels, may alter insulin signaling in different tissues." (PMID 33800465, 2021). "This negative feedback is believed to be co-opted by hyperinsulinemia, metabolic stress, and inflammation for the inhibition of insulin signaling." (PMID 33810179, 2021). "The links between autonomic indices and insulin levels and HOMA-IR could confirm the role of hyperinsulinemia in the sympathetic and vagal activity leading to hypertension." (PMID 34438577, 2021). "Insulin resistance syndrome occurs when tissues do not respond to insulin, which leads to hyperinsulinemia and a decrease in insulin transport through the BBB." (PMID 33809300, 2021). "In both obese mice and humans, hyperinsulinemia results in elevated adipose tissue cytokine levels, while this does not occur in healthy, non-obese and non-insulin resistant patients." (PMID 33992101, 2021). "Moderate pulsatile hyperinsulinemia in nondiabetic human subjects does not induce insulin insensitivity." (PMID 34360563, 2021). "Finally, we provide evidence that inhibition of insulin secretion mimics the TRF effect, whereas artificial elevation of insulin reverses it, suggesting that TRF acts by modulating hyperinsulinemia." (PMID 33495474, 2021). "Measurement of insulin in amniotic fluid or cord blood is not easy for detection of fetal hyperinsulinemia." (PMID 34893662, 2021). "Eventually, hyperinsulinemia will occur as a negative feedback from the target cells, signaling inadequate insulin response, and, in turn, the pancreatic β-cells will produce more insulin." (PMID 34576959, 2021). "Clinical studies have demonstrated that serum insulin level increases after AP and CP, although in both cases, hyperinsulinemia is explained by the decreased insulin clearance, and not by the overproduction of insulin." (PMID 34566890, 2021). "The CRL inhibitor MLN4924 specifically inhibits hyperinsulinemia in Csn2WT/K70E mice, without significantly affecting serum insulin levels in wild-type littermates." (PMID 33911083, 2021). "The Csn2WT/K70E mice we generated represent a rare nontransgenic model of “congenital hyperinsulinism”, whereby insulin oversecretion drives resistance." (PMID 33911083, 2021). "The negative consequences of insulin resistance and/or hyperinsulinemia are further exacerbated by the fact that NAFLD decreases hepatic insulin clearance, impairs glucose disposal, and increases hepatic glucose production." (PMID 32384593, 2020). "The use of a KATP channel activator which is capable of penetrating the DVC has the potential to recapitulate the effects of leptin, insulin and α-MSH, with the likely result being reductions in hyperinsulinemia, reductions in hepatic gluconeogenesis, reductions in appetite and improved satiety." (PMID 32326226, 2020).
Hyperinsulinemia (continued). "Comparable systemic insulin concentrations in empagliflozin treated and control mice further suggest that these effects do not result from improved systemic hyperinsulinemia." (PMID 33184414, 2020). "Interestingly, however, studies that have attenuated high-calorie diet-induced hyperinsulinemia in mice report reduced fat mass, attenuation of NAFLD, improved insulin sensitivity, and extended lifespan." (PMID 32350271, 2020). "Insulin resistant SGBS show only moderate changes in glucose uptake, highlighting once again how the different adipocyte background can influence the response to hyperinsulinemia." (PMID 32718202, 2020). "For example, the lack of CEACAM-1, a key protein enrolled in hepatic insulin clearance driving hyperinsulinemia, in the kidney leads to increased renin levels contributing to a potentiation of the RAS system and hypertension." (PMID 32850773, 2020). "We therefore conclude that lack of TMBIM6 does not affect insulin sensitivity but leads to hyperinsulinemia, which serves to explain the weight gain." (PMID 32394396, 2020). "In contrast, in female mice genotype did not significantly affect fasting blood glucose or insulin, but ovariectomy did, promoting hyperinsulinemia and increasing HOMA2-IR." (PMID 32720643, 2020). "Although insulin signaling is known to be essential to β-cell growth and function, possible long term negative autocrine actions of insulin (i.e., hyperinsulinemia) on β-cell function and mass are still controversial." (PMID 32150819, 2020). "Serum insulin concentration provides a reliable basis for the diagnosis, treatment, and monitoring of many diseases, especially hyperinsulinemia, in which the serum insulin concentration is higher than normal individuals." (PMID 32506749, 2020). "Yet, mealtime WP's influence on the regulation of hepatic lipid metabolism, which is sensitive to hyperinsulinemia and is upregulated in insulin-resistant states, is not known." (PMID 33195375, 2020). "We found that obese KO→WT mice show a trend toward higher fasting hyperinsulinemia (data not shown) and become more insulin resistant than their body weight–matched WT→WT controls, as shown by ITT and glucose tolerance test (data not shown)." (PMID 32973799, 2020). "The AS mice showed hyperinsulinemia during an ipGTT, and this effect was probably not due to alteration in their insulin sensitivity at peripheral tissues as confirmed by a hyperinsulinemic-euglycemic clamp experiment." (PMID 33324349, 2020). "Compensatory hyperinsulinemia during body mass gain does not appear to be sustainable over time since insulin was reversed at the end of life according to the current results." (PMID 32243710, 2020). "Interestingly, broad sense heritability for circulating insulin (0.153) was much lower than heritability for adiposity (0.383), which implies that environmental factors such as diet or lifestyle may have a stronger effect on attenuating hyperinsulinemia than adiposity." (PMID 33643372, 2020). "Insulin levels within the range of normal nondiabetic controls were observed to correlate with increased circulating miR-330-3p compared to hyperinsulinemia, observed to correlate with low levels of miR-330-3p in women with GDM." (PMID 31969632, 2020). "This could result in an increased reliance on insulin-mediated glucose uptake, via GLUT4 and subsequent hyperinsulinemia." (PMID 33210059, 2020). "Hyperinsulinemia has long been known as a driver of hepatic triglyceride synthesis, which accords with our present finding of concomitant reductions of OGTT insulin and fasting plasma triglycerides after our low intensity ambulation which otherwise is found after intensive exercise." (PMID 30785891, 2019). "Further, the EGF concentrations during acute laminitis (~46 hour samples) did not correlate with insulin concentration measured at the same time in these horses (r2 = -0.32; P = 0.50), which was not unexpected given the marked exogenous hyperinsulinemia." (PMID 31805097, 2019).
Hyperinsulinemia (continued). "Supporting this hypothesis is the observation that postprandial hyperinsulinemia was reduced after both CONT and INT exercise training, suggesting improved peripheral insulin sensitivity." (PMID 31976336, 2019). "Our diabetic animal were exposed to hyperinsulinemia until the time of IR, which was performed without insulin as this per se influences cardioprotection." (PMID 31151453, 2019). "In summary, a subset of (but not all) patients with DM1 present with hyperinsulinemia, which occurs during fasting, but also as an exaggerated (pro-)insulin response to carbohydrate intake." (PMID 31849810, 2019). "When fed with HFD, the suppression of HGP by hyperinsulinemia was 73% in Ad-GFP mice, but only ~48% in Ad-CILP-2 mice relative to NC-fed Ad-GFP mice (P < 0.05), indicating a marked decrease in hepatic insulin sensitivity." (PMID 30896018, 2019). "The effect of chronic high insulin on circadian period in cells is unlikely to be physiologically relevant, as sustained hyperinsulinemia is pathological in vivo." (PMID 31030999, 2019). "Although deletion of p110α, but not p110β, results in impaired muscle insulin signaling and hyperinsulinemia, these mice had normal whole-body glucose tolerance and insulin sensitivity." (PMID 31363081, 2019). "Similarly, insulin concentration shows significant differences in OZDF rats, in both fasting and later of the glucose load hyperinsulinemia was observed, that corresponding to 75%, 203%, 239%, 341, and 228% at 0, 30, 60, 90 and 120 min." (PMID 31905880, 2019). "It is of note that the patient’s physiological state on insulin therapy is not comparable to that of hyperinsulinemia." (PMID 31200528, 2019). "Interestingly, short-term hyperinsulinemia affected mostly the immune cell populations deregulated in FDR subjects, which suggests an important interplay between immune system homeostasis and insulin levels." (PMID 30983877, 2019). "In contrast, the chronic group showed a similar pattern of insulin secretion without hyperinsulinemia." (PMID 31126070, 2019). "The observed hyperinsulinemia and hyperleptinemia were highly correlated with HFCD-induced weight gain, recapitulating conditions in most overweight or obese individuals who have at least some degree of insulin and leptin resistance." (PMID 29651002, 2018). "In summary, 4-MEI induced hyperinsulinemia is not due to the increase in insulin synthesizing potential of existing cells but due to hyperplasia of beta cells." (PMID 30451881, 2018). "StarlixTM, on the other hand, designed to stimulate insulin secretion, had no beneficial effect on diabetic Nile rats presumably because the hyperinsulinemia already present does not benefit from further insulin production." (PMID 29463026, 2018). "It is important to mention that, in healthy women, inhibition of insulin secretion with diazoxide does not have any effect on their testosterone levels and hyperinsulinemia during a euglycemic-hyperinsulinemic clamp does not increase their androgen production." (PMID 29971102, 2018). "For example, hyperinsulinemia results in serine/threonine phosphorylation of IRS (which promotes IRS degradation) and prevention of tyrosine phosphorylation (which is the classic phosphorylation in insulin signaling pathways involved in PI3K→Akt→FOXO1)." (PMID 30602666, 2018). "This study aimed to determine if velagliflozin reduced hyperinsulinemia and prevented laminitis in insulin-dysregulated ponies fed a challenge diet high in non-structural carbohydrates (NSC)." (PMID 30212530, 2018). "Orally delivered insulin, similar to physiological insulin secretion, is transmitted directly from the intestine to the liver and does not lead to peripheral hyperinsulinemia, providing better glucose homeostasis." (PMID 30524677, 2018).
Hyperinsulinemia (continued). "While the plasma insulin levels were significantly reduced, the peritoneal MΦ Irs2 expression levels were significantly increased in the STZ plus phlorizin-treated mice, suggesting that hyperinsulinemia downregulates MΦ Irs2 expression in vivo." (PMID 30451856, 2018). "To study the effect of hyperinsulinemia on esophageal cancer development, we evaluated insulin signal transduction in esophageal tissue of non-operated animals at 13 weeks of age." (PMID 29662006, 2018). "In the first group with abstaining hyperinsulinemia, there was a worthy response to the glucose level by increasing insulin secretion, and in the second group, no response to the glucose administration was highlighted by fasting excessive insulin in the blood." (PMID 29805204, 2018). "The cancer-promoting effect of hyperinsulinemia is based on the knowledge that insulin has both metabolic and mitogenic actions via its own receptor in addition to the IGF-1R, which is activated by insulin with a much lower affinity." (PMID 30453495, 2018). "On the other hand, peripheral hyperinsulinemia does not necessarily result in increased levels of INS in CNS." (PMID 30274197, 2018). "Inositol reduces glycemia levels and hyperinsulinemia, while buffering negative effects of sustained insulin stimulation upon the adipose tissue and the endocrine system." (PMID 30595691, 2018). "The hyperinsulinemia measured in HFHS-fed rats could also favor this adipose tissue hypertrophy, since insulin inhibits lipolysis and promotes lipogenesis in adipocytes." (PMID 30261666, 2018). "Redox modulation by MnP treatment diminished serum insulin levels compared to HFD-fed mice at 5 and 10 weeks of HFD feeding, with a significant reduction seen by 12 weeks (p ≤ 0.05) indicating lessened hyperinsulinemia and improved utilization of insulin." (PMID 29104232, 2017). "Interestingly, inclusion of the nopal in HFS diet for 1 month resulted in a significant decrease in GIP and insulin concentrations, indicating that nopal can prevent GIP hypersecretion and hyperinsulinemia." (PMID 28680065, 2017). "Obese children have hyperinsulinemia and significantly lower insulin-stimulated glucose disposal than nonobese children." (PMID 29457038, 2017). "The HF mice displayed the significant hyperinsulinemia and hyperleptinemia (p < 0.001, p < 0.001, respectively), and TRR1-, TRR2-, TRR3-, Feno-, and Metf-treated mice significantly lowered levels of blood insulin and leptin." (PMID 29099085, 2017). "Long-term fructose feeding can induce compensatory hyperinsulinemia, whereas short-term fructose does not stimulate insulin secretion." (PMID 28629187, 2017). "In this study, we found that an important factor, insulin, could induce the overexpression of DHCR24 in endometrial cancer cells, which agrees with the finding that hyperinsulinemia is quite prevalent in EC7." (PMID 28112250, 2017). "The hyperinsulinemia phenotype is normalized by the restoration of Pomc in the subset of cells expressing 5-HT2CRs in Pomc5-HT2CR mice, indicating that Pomc synthesized in 5-HT2CR cells is sufficient to mediate POMC's effects on insulin sensitivity." (PMID 29031711, 2017). "GTT analysis revealed that at time zero, aged AAV-GFP mice showed higher insulin levels than their younger AAV-GFP counterparts, 1.56±0.31 ng/mL vs 0.41±0.08 ng/mL respectively, suggesting the development of age-related hyperinsulinemia." (PMID 28121620, 2017). "In addition, MCRI correlated significantly with both FSI and AUC-insulin during OGTT, again suggesting the contribution of MCRI to hyperinsulinemia at fasting and during OGTT." (PMID 28469173, 2017). "The current study indicates that reduced hepatic insulin clearance is not the only mechanism responsible for hyperinsulinemia, but also increased insulin gene-expression parallels the increase of serum glucose levels." (PMID 28134848, 2017).